GSAP (gamma-secretase activating protein)
Description:
Regulator of gamma-secretase activity, which specifically activates the production of amyloid-beta protein (amyloid-beta protein 40 and amyloid-beta protein 42), without affecting the cleavage of other gamma-secretase targets such has Notch. The gamma-secretase complex is an endoprotease complex that catalyzes the intramembrane cleavage of integral membrane proteins such as Notch receptors and APP (amyloid-beta precursor protein). Specifically promotes the gamma-cleavage of APP CTF-alpha (also named APP-CTF) by the gamma-secretase complex to generate amyloid-beta, while it reduces the epsilon-cleavage of APP CTF-alpha, leading to a low production of AICD.
Synonyms: PION; LOC54103
Tractability: PROTAC: its protein half-life has been measured; a small molecule that binds it is known.
Gene: Protein-coding gene on chromosome 7 (77,310,751 to 77,416,419, reverse strand). Ensembl gene ENSG00000186088.
Subcellular location: Golgi apparatus, trans-Golgi network
Subcellular location (Human Protein Atlas): Vesicles
Gene Ontology:
Molecular function: amyloid-beta binding; protein binding
Biological process: positive regulation of amyloid-beta formation; regulation of proteolysis
Cellular component: trans-Golgi network; Golgi apparatus
Genetic constraint (gnomAD): Loss-of-function variants: 21 observed, 25.2 expected, observed/expected ratio (o/e) 0.83, 90% interval 0.59 to 1.2. The upper end of that interval is the gene's LOEUF score, 1.2, which puts it in group 5 of 6, group 1 being the genes least tolerant of losing a copy. Missense variants: 275 observed, 260.41 expected, observed/expected ratio (o/e) 1.06, 90% interval 0.96 to 1.17. Synonymous variants: 111 observed, 100.22 expected, observed/expected ratio (o/e) 1.11, 90% interval 0.95 to 1.3.
Homologues: Orthologues: chimpanzee GSAP (99% identical), macaque GSAP (93% identical), dog GSAP (83% identical), pig GSAP (83% identical), rabbit GSAP (81% identical), mouse Gsap (75% identical), rat Gsap (73% identical), tropical clawed frog gsap (47% identical), zebrafish gsap (30% identical), Drosophila melanogaster pigeon (21% identical).
Diseases named in the same sentence as GSAP in open-access papers:
GSAP is named in the same sentence as 18 diseases in open-access papers, as found by Europe PMC text mining. Sharing a sentence is not in itself a finding about the gene and the disease. The quoted sentences say what the papers report.
Alzheimer disease (5 papers, 2015 to 2025). A progressive, neurodegenerative disease characterized by loss of function and death of nerve cells in several areas of the brain leading to loss of cognitive function such as memory and language. "Biochemical, pathogenic, and human genetic data confirm that GSAP (γ-secretase activating protein), a selective γ-secretase modulatory protein, plays important roles in Alzheimer’s disease (AD) and Down’s syndrome." (PMID 34156424, 2021). "The GSAP was identified as a γ-secretase-interacting partner, it could form a complex with γ-secretase and APP-CTF, and an SNP in GSAP has been discovered to be associated with Alzheimer’s disease, giving genetic evidence that links GSAP to AD susceptibility." (PMID 40927393, 2025). "GSAP plays an important role in Alzheimer's disease, but the underlying cellular and molecular pathways remain unclear." (PMID 34156424, 2021). "However, the γ-secretase activating protein (GSAP) has mostly been reported in the context of Alzheimer’s disease pathology." (PMID 32641122, 2020). "Taken together, our findings demonstrate that GSAP cleavage via caspase-3 is regulated and depend upon the availability of 5LO further establishing this protein as an attractive and viable therapeutic target for Alzheimer’s disease." (PMID 26076991, 2015). "In addition, GSAP (gamma-secretase activating protein) plays an important role in Alzheimer's disease by regulating lipid homeostasis and mitochondrial function, but its functional relevance in asthma is not largely unknown." (PMID 37875944, 2023).
lung carcinoma (2 papers, 2021 to 2023). "After GSAP antibody validation, we further performed an endogenous co-IP experiment using a Fe65 antibody and cell lysates from human lung carcinoma cell line A549, which has high endogenous expression of both GSAP and Fe65, and showed the co-IP of endogenous Fe65 with PP1 and GSAP." (PMID 34156424, 2021).
pulmonary arterial hypertension (2 papers, 2022 to 2023). Pulmonary arterial hypertension (PAH) is a group of diseases characterized by mean pulmonary artery pressure >20 mmHg and elevated pulmonary arterial resistance leading to right heart failure. "Our previous study showed that circular RNA-gamma-secretase-activating protein (circGSAP) was down-regulated in pulmonary microvascular endothelial cells (PMECs) in response to hypoxia, and regulated the cell cycle of PMECs via miR-942-5p sponge in pulmonary hypertension (PH)." (PMID 36403044, 2022).
amyloid (1 paper, 2021). "Silencing GSAP expression significantly reduced cellular γ-secretase activity and Aβ production in vitro; reduced CNS Aβ levels, amyloid plaque formation and pTau in AD mouse models, without altering other γ-secretase function such as Notch-dependent pathways." (PMID 34809709, 2021).
bacterial pneumonia (1 paper, 2023). Acute infection of the lung parenchyma caused by bacteria (e.g., Streptococcus pneumoniae, Haemophilus influenzae, Chlamydia pneumoniae, Mycoplasma pneumoniae, and Legionella pneumophila). "In conclusion, we provide evidence that bacterial pneumonia requires GSAP to orchestrate the molecular events underlying end-organ dysfunction in the lung and heart." (PMID 37366533, 2023). "Here, we tested the hypothesis that gamma-secretase activating protein (GSAP), which contributes to the amyloidogenic pathway in the brain, promotes end-organ dysfunction following bacterial pneumonia." (PMID 37366533, 2023).
cognitive deficits (1 paper, 2021). "Since J20 mice exhibit major cognitive deficits at 5–7 mo of age, we used 6-mo-old J20;WT and J20;GSAP−/− (J20;KO) mice for behavioral analysis." (PMID 34156424, 2021). "Increased GSAP mRNA expression with age supports previous findings that GSAP levels are significantly elevated in AD patient brain with severe pathology and cognitive deficits." (PMID 34156424, 2021).
dementia (1 paper, 2022). Loss of intellectual abilities interfering with an individual's social and occupational functions. "Not only the APP gene is responsible for dementia in DS, GATD3A, SOD1, ERG, BACE2, DSCR1/RCAN1, APOE (19q13.32), BACE1 (11q23.3), IL1B (2q14.1), GSAP (7q11.23), UBB (17p11.2), and IRS1 (2q36.3) genes may also play a major role in dementia in DS." (PMID 35676933, 2022).
depression (1 paper, 2022). "In summary, through observational and GWEIS analyses, this study indicated emotional care in childhood may affect the age at onset of depression, especially in males, and further identified GSAP as a candidate gene." (PMID 35879288, 2022).
Down syndrome (1 paper, 2021). "In addition to increased GSAP levels observed in AD mouse models, GSAP up-regulation has also been reported in neurodegenerative contexts such as Down’s syndrome, which is obligately associated with Aβ plaque pathology due to triplication of human chromosome 21 harboring APP." (PMID 34156424, 2021).
glioma (1 paper, 2022). A benign or malignant brain and spinal cord tumor that arises from glial cells (astrocytes, oligodendrocytes, ependymal cells). "Although glioma lines are not representative of LGGs, we found the expression of GSAP was consistent with that of fibroblasts, and the expression of the other four risk genes was lower than that of fibroblasts in glioma cell lines." (PMID 36727078, 2022). "GSAP and SWAP70 expressed similar levels in different cell lines, and the expression of the remaining three genes was lower in glioma cell lines." (PMID 36727078, 2022). "Compared to fibroblast cell lines and glioma cell lines using the CCLE database, we found that the expression of GSAP was similar." (PMID 36727078, 2022).
HIV-1 infection (1 paper, 2021). The type species of lentivirus and the etiologic agent of acquired immunodeficiency syndrome (AIDS). "qPCR analyses of GSAP also showed that HIV-1 infection increased GSAP mRNA in brain tissues by 13 to 15-fold compared to control animal groups (P < 0.0001)." (PMID 34809709, 2021).
myopia (1 paper, 2023). "GSAP and GRM5/TYR genes are associated risk factors for the development of PDS, PG, and myopia." (PMID 36979429, 2023).
neuronal tumor (1 paper, 2021). Neuronal brain tumors are an uncommon group of central nervous system tumors that arise from cells with neuronal differentiation. "To further investigate potential biological effects of GSAP–Fe65 interaction, we generated Fe65 KO (Fe65KO) neuronal tumor CAD cells by CRISPR-Cas9 editing." (PMID 34156424, 2021).
pneumonia (1 paper, 2023). An acute, acute and chronic, or chronic inflammation focally or diffusely affecting the lung parenchyma, caused by an infection in one or both of the lungs (by bacteria, viruses, fungi, or mycoplasma.). "Based on these studies, and the role that GSAP plays in regulating Aβ production in the brain, we sought to determine whether GSAP contributes to the host-pathogen response during infection, mediating end-organ dysfunction that is a consequence of pneumonia." (PMID 37366533, 2023).
tumor (3 papers, 2013 to 2025). "Analysis of the expression of the TILB-related signature genes in B Plasma cells showed that KMO, IFT57, HDAC9, GSAP, and CCR7 were significantly highly expressed in tumor tissue, while ZNF439 and KDM5D showed a similar trend." (PMID 40145017, 2025). "The results showed that ZNF439 and KDM5D were highly expressed in normal tissues, whereas KMO, FT57, HDAC9, GSAP, and CCR7 were highly expressed in tumor tissues." (PMID 40145017, 2025). "The expression of EMP3, GSAP, SLC2A10, and SWAP70 was higher in tumor periphery." (PMID 36727078, 2022).
infection (2 papers, 2023 to 2025). The state of being infected such as from the introduction of a foreign agent such as serum, vaccine, antigenic substance or organism. "Infection with Pseudomonas aeruginosa caused arterial hypoxemia in wild-type rats, but the integrity of the alveolar-capillary barrier was preserved in GSAP knockout rats." (PMID 40927393, 2025). "Nonetheless, infection-induced inhibition of LTP is mostly GSAP-independent, because the amount of inhibition in the presence or absence of GSAP expression was generally comparable." (PMID 37366533, 2023). "Additionally, infection enhanced myocardial infarction after ischemia-reperfusion injury, and this enhancement was eliminated in the GSAP knockout rats." (PMID 40927393, 2025). "Furthermore, hippocampi from knockout rats, and both the wild-type and knockout rats following infection, exhibited a GSAP-dependent increase in neurotransmitter release probability and postsynaptic hyperexcitability." (PMID 37366533, 2023). "Thus, GSAP dampens CA1 neuron excitability under basal conditions, and lung infection leads to hyperexcitability in both the wild-type and knockout CA1, suggesting that infection impairs GSAP function necessary to promote hyperexcitability." (PMID 37366533, 2023).
GSAP also shares sentences with these, for which no sentence is quoted: asthma (1 paper); pulmonary hypertension (1).